SOX2 (SRY-box transcription factor 2)
Diseases named in the same sentence as SOX2 in open-access papers (continued):
Sharing a sentence is not in itself a finding about the gene and the disease.
tumor (continued). "As important proteins of MAPK signaling pathway, ERK1/2 can modulate the migration and EMT of tumor cells through regulating ZEB1, SOX2, etc.." (PMID 36229838, 2022). "Both fludarabine and ruxolitinib treatments exhibit significant impact on the tumour growth of 22Rv1 line, and diminish the protein level of STAT1, BMI1, SOX2 and NANOG in 22Rv1 tumours when compared with vehicle control." (PMID 35908276, 2022). "Ultimately, we recommend conducting a further study to verify the interaction of Oct-4 and Sox-2 in MCT crossbred dogs because the co-expression frequently enhances the aggressiveness and progression of some human neoplasms." (PMID 34903921, 2021). "Silencing UCA1 or up-regulating miR-122-5p degraded SOX2 expression, and reduced invasion, migration and proliferation of CD133+CaSki cells while advanced apoptosis and suppressed the tumor volume and weight in nude mice." (PMID 34053467, 2021). "Three tumor samples (T5, T16, and T19) exhibited high-level amplification in 3q26, including WWTR1, TP63, PIK3CA, SOX2, SOX2-OT, and ZNF639 genes." (PMID 34285259, 2021). "In this study, we found that THL dramatically suppressed the DUB activity of PSMD14 (with little effect on other JAMM DUBs) and E2F1/Akt/SOX2 pathway, which spurred tremendous interests to exploit THL as an anti-tumor drug." (PMID 33456565, 2021). "Stem-like cells isolated from primary cervical tumours, capable of self-renewal, spheroid formation, and tumour initiation, were found to have high expression of CD44 and CK17 markers, ABCG2 drug transporter, and stemness related genes OCT4 and SOX2." (PMID 34283069, 2021). "Circ-ABCC3 regulates GBM angiogenesis and tumor malignancy progression through PI3K/AKT signaling pathway and miR-770-5p/SOX2 axis." (PMID 34881248, 2021). "Circ-ABCC3 acts as a sponge for miR-770-5p, which targets SOX2, and knockdown of Circ-ABCC3 significantly inhibits tumor growth in vivo." (PMID 34881248, 2021). "Strikingly, there were few tumor cells observed in mice injected with TRIM26 knockdown GSCs, precluding any robust quantitative analysis of SOX2 immunofluorescence in these brains." (PMID 34732716, 2021). "The reason for this is that H19 is activated by Sox2 (transcription factor SOX-2), and Sox2 is inhibited by TGF-β, whose levels are high in the tumor microenvironment." (PMID 34071216, 2021). "Our results demonstrate that zinc phthalocyanine (ZnPc)-PDT with 12 J/cm2 or 24 J/cm2 irradiation can substantially decrease tumor migration via downregulating MMP9 and ROCK1 and inhibit the clonogenicity of SW480 cells via downregulating CD44 and SOX2." (PMID 34833970, 2021). "Perinecrotic niches are enriched for cells expressing molecular markers of both hypoxia and GSCs (e.g. SOX2, NANOG, CD133) 24, 25, suggesting a connection between the tumor microenvironment and differentiation state of cells." (PMID 33391498, 2021). "c-MYC (green) was also co-expressed with NANOG (red), SOX2 (red) and KLF4 (red) by cells within the tumor glands (arrowheads)." (PMID 34685477, 2021). "Recently, it has been found that the expression of OCT4, SOX2, and KLF4 was high in CSC subpopulations within the tumor nests and peritumoral stroma of head and neck metastatic malignant melanoma." (PMID 35048028, 2021). "In a consistent way, Sox2 downregulation reduces invasive potential through a mesenchymal to epithelial transition (MET), enhances chemosensitivity and inhibits xenograft tumour growth in vivo." (PMID 34831291, 2021). "The expression of NANOG and OCT4 was evaluated by immunohistochemistry in 122 cases, SOX2 in 121 cases, Nestin in 93 cases and PDPN in 85 cases in which representative tumor tissue was available." (PMID 34201050, 2021). "SOX2, relative to OCT4 or NANOG, is a stronger indictor of chemoresistance, tumor-initiation, and recurrent disease." (PMID 33445692, 2021).
tumor (continued). "Further, BTK was found to be co-expressed to differing degrees with SOX2, CD163, or CD68, indicative of both tumour and immune cell expression of the kinase." (PMID 34645618, 2021). "In our study, SOX2 highly expressed in embryonic cells, and PEG10 highly expressed in embryonic and malignant tumour cells." (PMID 34775482, 2021). "In a flank tumor model using ONS76 MB cells, elevation of SOX2 from an inducible promoter led to a reversible state of tumor growth arrest." (PMID 35054230, 2021). "PI3K/Akt/mTOR inhibition reduces SOX2 and OCT4 protein levels and thereby self-renewal and tumor-initiating capacity in some cancers." (PMID 33828530, 2021). "Xenograft tumor of HCT 116 showed an increased expression of neuronal genes MAP2 and SYN1, neural stemness genes CDH2, MSI1, NCAM1, SOX2/9, VIM and ZEB2, and genes for mesodermal and endodermal tissues (ACP5, AFP, DESMIN, HNF4A and KRT8)." (PMID 33468253, 2021). "Similar to the supratentorial tumor cells, these tumor cells were positive for GFAP, SOX2, and ATRX." (PMID 34587990, 2021). "We examined the correlation between SOX2, Bax, or Bcl-2 expression with liver function tests (LFT), including AST, ALT, ALP, as well as alpha-fetoprotein (AFP) tumor marker." (PMID 34436030, 2021). "Depletion of SOX2, a pluripotency factor characteristic of ESCs and CSC, resulted in a dramatic decrease in sphere formation and tumor growth initiation." (PMID 33804155, 2021). "Since NANOG, SOX2 and KLF4 are essential for converting tumor cells into aggressive stem-like cells, an increase in the expression of these markers in our study after irradiation further supports the increased cancer stem cell population." (PMID 33419140, 2021). "The in vitro and in vivo assays suggested that PSMD14 depletion significantly impaired tumor growth, chemoresistance in HNSCC by antagonizing E2F1/Akt/SOX2 axis-mediated cancer cell stemness." (PMID 33456565, 2021). "We have previously identified two CSC subpopulations within mHNcSCC: an OCT4+/SOX2+/NANOG+/KLF4+/c-MYC+ subpopulation within the tumor nests (TNs) and an OCT4+/SOX2+/NANOG-/KLF4+/c-MYC+ subpopulation within the peritumoral stroma (PTS)." (PMID 34621666, 2021). "In lymph node metastases compared to the invasive front of the tumor, ONECUT2 and SOX2 were down-regulated, while PTPN13, TGFB2, ZEB2, RND3 and CDKN1B were up-regulated." (PMID 34046357, 2021). "We have previously shown an association between the expression of the embryonic transcription factor SOX2 and worse survival outcome in HGSC patients with tumor tissue remaining after primary debulking surgery." (PMID 34069138, 2021). "OCT4, SOX2 and NANOG, as the embryonic stem cell transcription factors, transform cancer cells to stem-like cell phenotype in different tumor types." (PMID 34150636, 2021). "They found that the tumor suppressor YY1 bound to the promoter of SOX2OT and inhibited tumor growth in vivo and in vitro by suppressing SOX2OT and SOX2 expression in PC." (PMID 34760707, 2021). "An analysis of patient data suggested a stronger role for SOX2, relative to OCT4 or NANOG, for tumor relapse potential." (PMID 33445692, 2021). "We also found GSC stemness-related genes, SOX2 and ID1, and MES subtype-related genes, THBS1 and CD44, enriched in the core of the tumours, together with higher TRIM28 expression." (PMID 34500575, 2021). "RPS6-KD suppressed the tumor-sphere formation of GBM cells through the inhibition of p-JAK2 and p-STAT3 and concomitantly downregulated the stemness-related proteins Nestin and SOX2." (PMID 35008473, 2021). "Slinomycin suppresses mammosphere formation and tumor growth in vivo via the inhibition of ALDH1 activity and downregulates the transcription factors Nanog, Oct4 and Sox2." (PMID 34381705, 2021). "The results revealed that most of the SRGs were differentially expressed and most of them were found increased in tumor tissues except for KIT, NGFR, SOX2 and KLF4 (sFigure 2A)." (PMID 34587919, 2021).
tumor (continued). "Our in vitro and in vivo studies indicated that SOX2, relative to OCT4 and NANOG, correlates with 3-D spheroid growth, tumor-initiating capacity, and chemoresistance." (PMID 33445692, 2021). "Actinomycin D (ActD) is an FDA-approved NCI oncology drug that specifically targets and downregulates the stem cell transcription factor SRY (sex determining region Y)-Box 2 (SOX2), which leads to stem cell depletion within the tumor bulk." (PMID 34577545, 2021). "Thereafter, the tumor spheres’ number, ALDH+ cell proportion, stemness genes (SOX2, OCT4, and NANOG), expression, and migratory cells were all reduced in MDA-MB-231-shLDHA cells." (PMID 34178639, 2021). "Immunofluorescence staining performed on three of the tissue samples showed co-expression of OCT4 and c-MYC with NANOG, SOX2 and KLF4 by tumor gland cells, and expression of OCT4 and c-MYC exclusively by cells within the stroma." (PMID 34685477, 2021). "This tumor cell-specific pseudobulk expression analysis also revealed a significant correlation between TRIM26 and SOX2 expression with a trend towards correlation in a second scRNA-seq dataset." (PMID 34732716, 2021). "Using a second set of GBM tumor samples (n = 20, samples frozen at –80°C), we used dual-label immunofluorescence to evaluate the expression of FOXO3 and SOX2 within the same tumor region and cell." (PMID 36303712, 2021). "We first determined the interaction between SOX2 and CCAT1 and that between miR-222-5p and CYLD and their effect on tumor growth in vivo was analyzed in HCC-xenograft bearing nude mice xenografts." (PMID 33952719, 2021). "At the same time, FoxM1 is closely related to the expression levels of stem cell markers such as Nanog, Sox2 and OCT4 in tumor samples, and promoted the expression of these stem-related genes in vitro." (PMID 33588867, 2021). "Among all tumor samples, the overall accordance rates, which combine the results of Gli1-negative and Gli1-positive samples, between Gli1 and BMI1 or SOX2 expression were 85% and 84%, respectively." (PMID 33499351, 2021). "IF staining demonstrated co-expression of OCT4 (green) with NANOG (red), SOX2 (red) and KLF4 (red) by cells within the tumor glands (arrowheads)." (PMID 34685477, 2021). "The core regulatory network for embryonic stem cell maintenance and self-renewal OCT4, SOX2, KLF4, NANOG, and SALL4 are abnormally expressed in human tumor samples suggesting the presence of cancer stem cells." (PMID 34249759, 2021). "By generating the heat map, two groups were identified: Group 1 contained tumour samples with high expression of BMI-1/CD44, and low expression of ALDH1/Nanog/SOX2, which correlated significantly with a higher grading (G1 vs. G2/3; p = 0.029)." (PMID 33009929, 2021). "Analysis of human tumor tissue spatial gene expression patterns showed distinct expression of SFRP2- and SOX2-correlated genes in vascular and cellular areas, respectively." (PMID 34021259, 2021). "The transcription factor SOX2, downstream of PI3K/AKT signaling, has been shown to regulate cell stemness and promote cell proliferation in several tumor types 38-40." (PMID 33408794, 2021). "On the 22nd day after injection, mice injected with SW620 control cells produced larger tumors (~800 mm3) than mice injected with SOX2-silenced SW620 cells (~300 mm3), indicating that SOX2 knockdown markedly decreased tumor growth." (PMID 33953166, 2021). "Using mRNA expression data from 20 primary tumor samples, we found that the mRNA expression levels of DNMT1, FOXM1, and SOX2 were significantly increased in tumor tissues." (PMID 31296961, 2020).
tumor (continued). "In contrast, in the one animal treated with A1016 and that still presented a small tumor of 0.6 mm in diameter, the tumor remained BMI1 and SOX2 positive, although EZH2 levels were reduced." (PMID 31934644, 2020). "Expression of specific markers OCT4, NANOG and SOX2 was increased in PT291 organoids and CLOs compared to the 2D primary cell lines, while PT127 PDX tumour had a similar expression profile to the PT127 CLOs compared to its 2D primary cell line." (PMID 32066753, 2020). "On the other hand, in LK0902 and LK0917 tumor cells from tumor cell/CAF spheroids, a tendency to an increase in mRNA expression of NANOG and SOX2 was observed." (PMID 33353547, 2020). "Immunohistochemistry of tumor samples from an orthotopic mouse model by double staining of BPA and a stem marker (SOX2 or Nestin) or differentiation marker, GFAP, revealed that all SOX2- or Nestin-positive GSLCs were also positive for BPA." (PMID 33086625, 2020). "Fursultiamine suppress OCT-4, SOX-2, NANOG expression and decreased ABCB1 and ABCG2 in tumor spheres." (PMID 33665161, 2020). "In the next step, expression level of stemness relatedgenes (OCT4, SOX2, KLF4, c-MYC and NANOG) and EMTtranscription factors (CDH1, CDH2, SNAIL1, TWIST1,TWIST2 and ZEB1) were evaluated in all tumor samples andmammospheres." (PMID 31376329, 2020). "Silencing METTL3 expression reduces SOX2 expression and, as a result, inhibits GBM tumor growth and prolongs the survival of mice." (PMID 32404927, 2020). "To support these findings, we tried to measure the amounts of acetyl-CoA in tumor tissues and detect the levels of p-ATM and SOX2." (PMID 32641713, 2020). "Sox2, as a YAP upstream regulator, was reported to be required for tumor development and cancer cell proliferation in OS." (PMID 32855654, 2020). "When compared to the tumor of control mice, the tumor of PTC596-treated mice with relapse (mice #5 and #6) had lost many the original characteristics, including reduced BMI1, EZH2, and SOX2 expression." (PMID 31934644, 2020). "By additional knockdown of SOX2 in PRL-3-overexpressing cells, tumor sphere induction assay and ALDEFLUOR assay showed that silencing of SOX2 almost blocks PRL-3's effect." (PMID 31887658, 2020). "It was described that POU3F2, SOX2, SALL2, and OLIG2 maintain the tumor-forming capability of these cells." (PMID 32634135, 2020). "Knockdown of IL-17RB, MUC1 and/or MUC4 also suppresses expression of stemness-related markers, such as SOX2, Nanog, Oct-4, and CD44, and inhibited tumor sphere formation." (PMID 33082357, 2020). "Previous study of >50 tumor samples and SCLC cell lines showed that SOX2 was amplified in approximately 27% of cancers." (PMID 32130794, 2020). "We were therefore able to analyze the expression of NANOG, SOX2, OCT4, AGR2, KLF4, and NOTCH1 in only 11 tumor samples and corresponding TANT (22 FFPE tissue samples)." (PMID 32733958, 2020). "SOX2 is known to regulate MM CSC self-renewal and tumorigenicity, as well as contributing to tumor invasion." (PMID 33147716, 2020). "Signaling elicited by the stem cell factors SOX2, OCT4, KLF4, and MYC not only mediates reprogramming of differentiated cells to pluripotency but has also been correlated with tumor malignancy." (PMID 32427884, 2020). "Taking advantage of the distinct origin of tumor (human) and stromal (murine) cells in our xenografts, we approached the evaluation of stemness genes NANOG, POU5F1 (OCT4), PROM1 (CD133) and SOX2, from the tumor origin." (PMID 32230715, 2020). "In glioblastome, SOX2 induces DNMT expression and methylation events that repress tumor suppressor miRNAs, which in turn promotes tumor propagation." (PMID 31296961, 2020). "Lewisx, Sox2, ALDH and CD44 expression, tumorsphere formation, resistance to 5-FU treatment and in vivo tumor growth were increased in FUT9-expressing MC38 cells compared to the control cells." (PMID 32927726, 2020).
tumor (continued). "As expected, tumor sphere formation assays determined that circPTN promoted increased levels of stemness markers, such as Nestin, CD133, SOX2, and SOX9, and tumor growth in vitro and in vivo, primarily via sponging miR-145-5p/miR-330-5p." (PMID 32528957, 2020). "A constitutive activation of PI3K/AKT signaling is also frequently seen in cancer, where SOX2 expression functionally coincides with the CSC compartment and its implication in treatment resistance, tumor dissemination, and relapse." (PMID 32664542, 2020). "Administrating mithramycin in vivo markedly reduced expression of SOX2, OLIG2, and ZEB1, which coincided with dramatic reductions in tumor growth." (PMID 31910904, 2020). "In tumor xenograph studies, SNC also reduced expression of Wnt target genes including CD44, Sox2 and LGR5." (PMID 33347461, 2020). "Our results showed that high expression of both SOX2 and SOX9 were significantly correlated with larger tumor size, tumor multiplicity, higher tumor grade, pathological stage and poor overall survival in univariate analysis." (PMID 33112555, 2020). "Like ZSCAN4, embryonic factors OCT3/4, SOX2, and NANOG are reactivated in cancer and have further been classified as CSC markers that regulate self-renewal and contribute to tumor aggressiveness and metastasis." (PMID 32507861, 2020). "The miRNA mediated silencing of SOX2 in GBM and NB tumor-initiating cells has been shown to stop their proliferation, leading to loss of tumorigenicity." (PMID 32092088, 2020). "In summary, we found m6A modification of AFF4 RNA was upregulated by METTL3 and their expression was elevated in BCSCs, which in turn promotes the expression of SOX2 and MYC to enhance tumorigenesis and tumor-initiating capacity of BCa." (PMID 32676121, 2020). "SOX2, OCT4 and Nanog pluripotency genes were evaluated by RT-qPCR following tumor cell stimulation with rIGF-1 or conditioned media, with similar levels of transcripts found under all conditions and stimuli." (PMID 32899449, 2020). "We previously have isolated the SOX2‐positive cervical CSC from SiHa and C33A, which exhibited the major characteristics of CSC, including self‐renewal, differentiation and tumour progression properties." (PMID 32954681, 2020). "Immunofluorescence staining of two HNmMM tissue samples demonstrated expression of PRR and AT2R by the SOX2+ CSCs within the TNs and the OCT4+ CSCs within the PTS, with ACE localized to the endothelium of the tumor microvessels within the PTS." (PMID 33147716, 2020). "Tumor tissue was taken out from nude mice for histology, and the protein expression level of OCT4 and SOX2 was detected by immunohistochemistry." (PMID 32788883, 2020). "This idea also signals to the notion that both epigenetic and genetic dysregulations of SOX2 might contribute to high plasticity and heterogeneity of neoplastic cells by facilitating formation of CSCs, as these cells were known to generate intra-tumor heterogeneity." (PMID 30517668, 2020). "Surprisingly, as the passage of the tumor-derived cells (TDCs) increased, the expressions of stem cell markers such as Oct4, CD133, and Sox2 decreased rapidly while the expression levels of oncogenes including c-Myc, Klf4 and ABCG2 were maintained." (PMID 31727938, 2019). "We designed a strategy to express in all tumor cells PLuc and eGFP reporters and, RLuc, RFP and tTK genes in the subpopulation of GSCs with active CD133 or OCTA4/SOX2 promoters." (PMID 31267022, 2019).